OR8A1 (olfactory receptor family 8 subfamily A member 1)
Description:
Odorant receptor.
Synonyms: OST025; OR11-318
Tractability: Antibody: UniProt places it where antibodies can reach, with medium confidence; UniProt predicts a signal peptide or a membrane-spanning region; its Gene Ontology location is reachable by antibodies, with medium confidence.
Gene: Protein-coding gene on chromosome 11 (124,566,660 to 124,582,942, forward strand). Ensembl gene ENSG00000196119.
Subcellular location: Cell membrane
Pathways (Reactome):
Sensory Perception: Expression and translocation of olfactory receptors
Gene Ontology:
Molecular function: olfactory receptor activity; G protein-coupled receptor activity
Biological process: G protein-coupled receptor signaling pathway; sensory perception of smell; detection of chemical stimulus involved in sensory perception of smell
Cellular component: plasma membrane; membrane
Genetic constraint (gnomAD): Loss-of-function variants: 6 observed, 15.76 expected, observed/expected ratio (o/e) 0.38, 90% interval 0.21 to 0.75. The upper end of that interval is the gene's LOEUF score, 0.75, which puts it in group 3 of 6, group 1 being the genes least tolerant of losing a copy. Missense variants: 354 observed, 395.9 expected, observed/expected ratio (o/e) 0.89, 90% interval 0.82 to 0.98. Synonymous variants: 156 observed, 159.49 expected, observed/expected ratio (o/e) 0.98, 90% interval 0.86 to 1.12.
Homologues: Orthologues: chimpanzee OR8A1 (99% identical), macaque OR8A1 (96% identical), dog OR8A1 (89% identical), rat Or8a1b (87% identical), rat Or8a1 (87% identical), mouse Or8a1b (85% identical), mouse Or8a1 (71% identical), tropical clawed frog or5dd2b (44% identical). Paralogues in human: OR8D4 (65% identical), OR8G5 (65% identical), OR8D2 (64% identical), OR8G3 (64% identical), OR8B3 (63% identical), OR8G1 (63% identical), OR8B2 (63% identical), OR8D1 (63% identical), OR8G2P (63% identical), OR8B8 (60% identical), OR8B12 (59% identical), OR8B4 (57% identical), and 84 more.